ARID5B (AT-rich interaction domain 5B)
Description:
Transcription coactivator that binds to the 5'-AATA[CT]-3' core sequence and plays a key role in adipogenesis and liver development. Acts by forming a complex with phosphorylated PHF2, which mediates demethylation at Lys-336, leading to target the PHF2-ARID5B complex to target promoters, where PHF2 mediates demethylation of dimethylated 'Lys-9' of histone H3 (H3K9me2), followed by transcription activation of target genes. The PHF2-ARID5B complex acts as a coactivator of HNF4A in liver. Required for adipogenesis: regulates triglyceride metabolism in adipocytes by regulating expression of adipogenic genes. Overexpression leads to induction of smooth muscle marker genes, suggesting that it may also act as a regulator of smooth muscle cell differentiation and proliferation. Represses the cytomegalovirus enhancer.
Synonyms: MRF-2; DESRT; MRF2; FLJ21150
Tractability: Antibody: the Human Protein Atlas places it where antibodies can reach. PROTAC: UniProt records ubiquitination sites on it; ubiquitination databases record sites on it.
Safety:
Unwanted effects reported when the protein is acted on. In parentheses: how it was acted on, where the effect was seen, and who reports it.
leukopenia (source: ClinPGx)
require glucarpidase treatment (source: ClinPGx)
Gene: Protein-coding gene on chromosome 10 (61,901,684 to 62,096,944, forward strand). Ensembl gene ENSG00000150347.
Subcellular location: Nucleus
Subcellular location (Human Protein Atlas): Endoplasmic reticulum; Cytosol; Nucleoplasm; Plasma membrane
Pathways (Reactome):
Chromatin organization: HDMs demethylate histones
Gene Ontology:
Molecular function: DNA binding; protein binding; transcription cis-regulatory region binding; transcription coactivator activity
Biological process: negative regulation of transcription by RNA polymerase II; transcription initiation-coupled chromatin remodeling; adipose tissue development; liver development; negative regulation of DNA-templated transcription; regulation of transcription by RNA polymerase II; positive regulation of DNA-templated transcription
Cellular component: catalytic complex; nucleoplasm; nucleus
Genetic constraint (gnomAD): Loss-of-function variants: 13 observed, 97.78 expected, observed/expected ratio (o/e) 0.13, 90% interval 0.086 to 0.21. The upper end of that interval is the gene's LOEUF score, 0.21, which puts it in group 1 of 6, group 1 being the genes least tolerant of losing a copy. Missense variants: 1,209 observed, 1,535.8 expected, observed/expected ratio (o/e) 0.79, 90% interval 0.75 to 0.82. Synonymous variants: 555 observed, 602.98 expected, observed/expected ratio (o/e) 0.92, 90% interval 0.86 to 0.99.
Homologues: Orthologues: chimpanzee ARID5B (99% identical), macaque ARID5B (98% identical), guinea pig ARID5B (93% identical), pig ARID5B (92% identical), mouse Arid5b (88% identical), dog ARID5B (88% identical), rabbit ARID5B (86% identical), rat Arid5b (82% identical), Drosophila melanogaster htk (20% identical), Caenorhabditis elegans arid-1 (10% identical). Paralogues in human: ARID5A (16% identical), ARID4B (15% identical), ARID4A (14% identical).
Diseases named in the same sentence as ARID5B in open-access papers:
ARID5B is named in the same sentence as 73 diseases in open-access papers, as found by Europe PMC text mining. Sharing a sentence is not in itself a finding about the gene and the disease. The quoted sentences say what the papers report.
acute lymphoblastic leukemia (21 papers, 2014 to 2025). Leukemia with an acute onset, characterized by the presence of lymphoblasts in the bone marrow and the peripheral blood. "While this gene has not previously been associated with head and neck cancer risk, germline variation in ARID5B has been implicated in acute lymphoblastic leukemia (ALL), as well as treatment resistance and higher rates of relapse." (PMID 36199081, 2022). "ARID5B is also known to contribute to cell growth, the differentiation of B-lymphocyte progenitors and has additionally been linked to acute lymphoblastic leukaemia." (PMID 33933144, 2021). "The genetic variants of the ARID5B gene have recently been reported to be associated with disease susceptibility and treatment outcome in childhood acute lymphoblastic leukemia (ALL)." (PMID 33499894, 2020). "Mutations and single nucleotide polymorphisms of AT-rich interactive domain-containing protein 5B (ARID5B) are involved in the oncogenesis of acute lymphoblastic leukemia (ALL) and treatment outcomes." (PMID 30420689, 2018). "This includes for example for bendamustine ARID5B associated with susceptibility of childhood acute lymphoblastic leukemia and treatment outcome, CD38 associated with cell survival and proliferation in chronic lymphocytic leukemia, and the oncogene MYB involved in different leukemias." (PMID 41146244, 2025). "An example of low penetrance common genetic variations associated with cancer risk includes IKZF1 and ARID5B genes in pediatric acute lymphoblastic leukemia (ALL)." (PMID 34155975, 2021). "ARID5B mutations /SNPs (single nucleotide polymorphisms) are reported to be involved in the oncogenesis of acute lymphoblastic leukemia (ALL) and treatment outcome." (PMID 30420689, 2018). "This study aimed to evaluate the association of single nucleotide polymorphisms (SNPs) in IKZF1, ARID5B, and CEBPE with acute lymphoblastic leukemia (ALL) susceptibility in Chinese children." (PMID 41488748, 2025). "By conducting genome-wide association studies (GWASs), we and other independent groups identified multiple top inherited predispositions to acute lymphoblastic leukemia (ALL) susceptibility, including single nucleotide polymorphisms (SNPs) at ARID5B, IKZF1, GATA3 and etc.." (PMID 33193587, 2020). "More recently, genome wide association studies identified significant associations between genetic polymorphisms in ARID5B e IKZF1 and acute lymphoblastic leukaemia, but only a few studies have replicated these results until now." (PMID 26045716, 2015). "Genome wide association studies (GWAS) have established association of ARID5B and IKZF1 variants with childhood acute lymphoblastic leukemia (ALL)." (PMID 25310577, 2014). "ARID5B influences antimetabolite drug sensitivity and prognosis of acute lymphoblastic leukaemia." (PMID 32063749, 2020). "Common allelic variants in IKZF1 (7p12.2), ARID5B (10q21.2), and CEBPE (14q11.2), which are directly related to hematopoietic differentiation and development, have been repeatedly and significantly associated with childhood acute lymphoblastic leukemia (ALL)." (PMID 24564228, 2014). "In TAL1-positive T-cell acute lymphoblastic leukemia (T-ALL) cell lines, the TAL1 complex aberrantly activates SEs within the ARID5B locus, contributing to the development of T-ALL." (PMID 40895527, 2025). "In parallel, we detected repression of pro-apoptotic mediator/tumor suppressors ID4 and ARID5B, downregulation of which correlates with enhanced acute lymphoblastic leukemia (ALL) cell proliferation." (PMID 37680627, 2023). "Interaction between the SNP rs10740055 (ARID5B) and maternal use of home insecticides during pregnancy, preconception paternal smoking, breastfeeding, repeated early common infections and birth order, in their relation with childhood acute lymphoblastic leukemia." (PMID 25806972, 2015).
acute lymphoblastic leukemia (continued). "Genome-wide association studies (GWAS) have identified that frequent polymorphisms in ARID5B and IKZF1, two genes involved in lymphoid differentiation, increase the risk of childhood acute lymphoblastic leukemia (ALL)." (PMID 25806972, 2015). "Association between childhood acute lymphoblastic leukemia (ALL), rs10740055 (ARID5B), rs4132601 (IKZF1), and the non-genetic factors of interest, in the ESCALE study, France 2003–2004." (PMID 25806972, 2015). "Our results confirmed the role of ARID5B in childhood ALL susceptibility among Hispanics; however, our assessment did not reveal any strong novel inherited genetic risks for acute lymphoblastic leukemia among this ethnic group." (PMID 28817678, 2017). "The SNPs (IKZF1 rs11978267, ARID5B rs10821936 and rs10994982, CEBPE rs2239633) were genotyped in 265 cases [169 acute lymphoblastic leukemia (ALL) and 96 acute myeloid leukaemia (AML)] and 505 controls by Taqman allelic discrimination assay." (PMID 24564228, 2014).
leukemia (13 papers, 2014 to 2025). A malignant (clonal) hematologic disorder, involving hematopoietic stem cells and characterized by the presence of primitive or atypical myeloid or lymphoid cells in the bone marrow and the blood. "Mutations of ARID5B might be a potential cofactor in patients with ETV6-linked leukemia predisposition." (PMID 35870987, 2022). "Therefore, further investigation is awfully needed to focus on delving into the underlying mechanism of ARID5B SNPs in different neoplastic settings, facilitating the clarification of the role ARID5B plays in the etiology of leukemia and autoimmune diseases." (PMID 32595701, 2020). "Additionally, several studies have reported the association of ARID5B with B-ALL leukemia risk." (PMID 37483604, 2023). "Here, we studied ARID5B expression in patients with ALL and discovered that ARID5Blow expression is linked to the markers of leukemia cell proliferation and that ARID5BlowPHF2low expression is possibly a poor prognostic indicator in patients with ALL." (PMID 30420689, 2018). "qChIP assay confirmed Ikaros recruitment at ARID5B promoter in the leukemia cell lines and primary cells." (PMID 30420689, 2018). "In Chr 10q21, variations in JMJD1C are related to platelet count (P = 2.0 × 10-24), those in ARID5B with leukemia (P = 7.0 × 10-19), and those in C10orf107 with blood pressure (P = 2.0 × 10-18)." (PMID 25689165, 2015). "The heterozygous genotype in ARID5B rs10821936 increased the risk for MLL-r leukemia in both white and non-white (OR 2.06, 95% CI: 1.12-3.79 and OR 2.36, 95% CI: 1.09-5.10, respectively)." (PMID 24564228, 2014). "The heterozygous/mutant genotype in the other ARID5B rs10994982 also significantly increased the risk for MLL-germline leukemia in white and non-white children (OR 2.60, 95% CI: 1.09-6.18 and OR 3.55, 95% CI: 1.57-8.68, respectively)." (PMID 24564228, 2014). "The heterozygous/mutant genotype in ARID5B rs10994982 significantly increased the risk for MLL-germline leukemia in white and non-white children (OR 2.60, 95% CI: 1.09-6.18 and OR 3.55, 95% CI: 1.57-8.68, respectively)." (PMID 24564228, 2014). "The mutant genotype in ARID5B SNP rs10821936 significantly increased the risk for MLL-germline leukemia in white and non-white children (OR 2.69, 95% CI: 1.28-5.66 and OR 3.69, 95% CI: 1.57-8.68, respectively)." (PMID 24564228, 2014). "Additionally, although cell cycle progression is highly associated with the drug sensitivity of leukemia cells, no clear association was observed between cell cycle progression and genotypes of the relapse-linked SNPs of ARID5B in BCP-ALL cell lines." (PMID 33499894, 2020). "The results corroborate with those obtained after stratification, showing that IKZF1 and ARID5B rs10994982 variant alleles play a role in the susceptibility to MLL-germline leukemia while ARID5B rs10821936 confers increased risk to both MLL-germline and MLL-r leukemia." (PMID 24564228, 2014). "One of the most significant findings from this study is that ARID5B rs10821936 not only differed between EAL and control groups but also distinguished MLL-MLLT3 positive leukemias from other MLL-r." (PMID 24564228, 2014).
Obesity (12 papers, 2014 to 2024). Accumulation of substantial excess body fat. "For example, an obesity-associated FTO variant (rs1421085) was found to disrupt an ARID5B repressor motif in an enhancer for IRX3/IRX5 during adipocyte differentiation, increasing obesity risk." (PMID 30617125, 2019). "The proposed causal allele was shown to alter an ARID5B repressor motif, leading to activation of the distant IRX3 and IRX5 in adipocyte precursor cells, and pro-obesity consequences for adipocyte thermogenesis regulation [23•]." (PMID 28758174, 2017). "Our results suggest that Arid5b may be a potential target for the treatment of metabolic diseases, including diabetes and obesity." (PMID 36743919, 2022). "We demonstrated previously that AT-rich interactive domain 5b (Arid5b) knockout (Arid5b−/−) mice were lean and resistant to high-fat diet (HFD)-induced obesity." (PMID 33023658, 2020). "The potential involvement of Arid5b in glucose metabolism through TBC1D1 would provide a new insight in the treatment of diabetes and obesity." (PMID 33023658, 2020). "Mice lacking ARID5B had reduced white fat mass and were resistant to obesity induced by a high-fat diet." (PMID 36672909, 2023). "Interestingly, we found that Arid5b−/− mice had reduced white adipose tissue mass relative to Arid5b wild-type (Arid5b+/+) mice and were resistant to high-fat diet (HFD)-induced obesity." (PMID 33023658, 2020).
atherosclerosis (10 papers, 2017 to 2024). A disease characterized by the build-up of fatty material and calcium deposition in the arterial wall resulting in partial or complete occlusion of the arterial lumen. "Of the specific top‐listed differentially expressed genes, two upregulated genes, CX3CR1 and ARID5B, have been previously associated with atherosclerosis." (PMID 32107839, 2020). "ARID5B CpG (cg25953130) methylation is inversely associated with both ARID5B expression and atherosclerosis, consistent with this CpG residing in an ARID5B enhancer region, based on chromatin capture and histone marks data." (PMID 28855511, 2017). "Jointly, the associations of ARID5B gene expression and methylation levels with atherosclerosis explain an additional 2.3% of the variability in carotid plaque score beyond well-known CVD risk factors and statin use." (PMID 28855511, 2017). "Here, the authors examine CD14+ blood monocyte’s transcriptome and epigenome signatures to find differential methylation and expression of ARID5B to be associated with human atherosclerosis." (PMID 28855511, 2017). "Our mediation analysis further suggests that the ARID5B methylation association with atherosclerosis is possibly via an epigenetically controlled enhancer that supports promoter activation and ARID5B transcription." (PMID 28855511, 2017). "Similarly, a study of blood monocytes transcriptome and epigenome revealed loci associated with atherosclerosis and identified a methylation mark in the ARID5B (AT-Rich Interaction Domain 5B) gene." (PMID 36247456, 2022). "Additionally, we found elevated gene expression associated with cell motility, including the CX3CR1 and ARID5B genes, which have been associated with the development of atherosclerosis." (PMID 32107839, 2020). "Expression levels of two genes were associated with atherosclerosis at both sites: ARID5B (AT-rich interactive domain-containing protein 5B), a transcriptional co-activator involved in metabolic activities such as adipogenesis and PDLIM7 (PDZ and LIM domain protein 7) which promotes mineralization." (PMID 32582174, 2020). "A recently longitudinal study showed ARID5B (transcription coactivator for histone H3K9me2 demethylation) CpG methylation is inversely associated with both ARID5B expression and atherosclerosis in human CD14+ blood monocyte, while the associations vanished in T cell samples from the same subset." (PMID 29410709, 2018). "CD14+ blood monocyte transcriptome and epigenome signatures suggest that ARID5B expression, possibly regulated by an epigenetically controlled enhancer, promotes atherosclerosis by dysregulating immunometabolism towards a chronic inflammatory phenotype." (PMID 35534881, 2022). "Folic acid plays a protective role against atherosclerosis through the regulation of DNA methylation, ARID5B expression, and monocyte subsets." (PMID 35227297, 2022). "Collectively, our findings suggest that increased ARID5B expression promotes atherosclerosis by dysregulating immunometabolism towards a chronic inflammatory phenotype." (PMID 28855511, 2017). "In lipopolysaccharide-stimulated human THP1 monocytes, ARID5B knockdown reduced expression of genes involved in atherosclerosis-related inflammatory and lipid metabolism pathways, and inhibited cell migration and phagocytosis." (PMID 28855511, 2017). "ARID5B was confirmed to involve in the formation of inflammation and thrombosis in atherosclerosis." (PMID 38224186, 2024). "The expression of ARID5B in monocytes of the elderly (>65 years old) was significantly up-regulated, which may be related to atherosclerosis." (PMID 36703979, 2022). "The AT-Rich Interaction Domain 5B (ARID5B) gene encodes a member of the AT-rich interaction domain (ARID) family of DNA binding proteins and methylation of ARID5B prevents inflammation and progression and development of atherosclerosis by inhibiting the ox-LDL/PI3K/Akt/NF-κB pathway." (PMID 35203642, 2022).
atherosclerosis (continued). "In particular, we identified a novel molecular link between ARID5B (transcription coactivator for histone H3K9me2 demethylation) mRNA expression and atherosclerosis, as well as the ARID5B CpG DNA methylation alteration that was inversely associated with both ARID5B expression and atherosclerosis." (PMID 28855511, 2017). "Expression of two genes, ARID5B and PDLIM7 (PDZ and LIM domain protein 7), were positively associated with both measures of atherosclerosis (FDR ≤ 0.05); ARID5B was most significantly associated with carotid plaque score (P = 6.30 × 10−8, FDR = 1.08 × 10−3; with CAC: P = 2.47 × 10−5, FDR = 0.03)." (PMID 28855511, 2017).
autoimmune disease (6 papers, 2020 to 2024). A disorder resulting from loss of function or tissue destruction of an organ or multiple organs, arising from humoral or cellular immune responses of the individual to their own tissue constituents. "ARID5B‐bound regions are predominantly associated with active transcription, and lncRNA dysfunction has been shown to lead to autoimmune disorders and may contribute to APS." (PMID 38224186, 2024). "ARID5B encodes a DNA-binding protein with roles in NK cell function, cancers of both B and T lymphocytes, and autoimmune disease." (PMID 38288162, 2023). "Genetic variants in ARID5B have also been linked to autoimmune diseases, suggesting that immune dysregulation may be a plausible pleiotropic mechanism at this locus, especially given the infectious etiology of oropharyngeal carcinoma." (PMID 36199081, 2022). "Of 223 hypomethylated regions identified, several were in promoters of autoimmune disease GWAS loci (ARID5B, CD69, HDAC9, IL7R, TNIP1 and TRAF1)." (PMID 32231389, 2020).
diabetes (5 papers, 2017 to 2024). "Specifically in β-cells, TG-induced stress resulted in increased expression of ARID5B (part of demethylase complex), MAP1LC3A (Mitophagy), and CLIC1 (chloride channel) expression and decreased G6PC2 and HADH, which have been associated with diabetes." (PMID 38956087, 2024).